BRAF (B-Raf proto-oncogene, serine/threonine kinase)
Diseases named in the same sentence as BRAF in open-access papers (continued):
Sharing a sentence is not in itself a finding about the gene and the disease.
melanoma (continued). "We, and others, have previously demonstrated that increased melanoma ctDNA levels and the appearance of circulating mutations associated with of acquired resistance, provide highly specific, early information of relapse during BRAF targeted therapies." (PMID 33216826, 2020). "However, 61% of the melanomas analyzed had a BRAF mutation, and the majority corresponded to the LM histological subtype and ALM." (PMID 32775409, 2020). "The progression from a premalignant lesion to melanoma is accompanied by an increase in the number of mutations in the MAPK pathway; in this study, 76% of invasive melanomas presented mutations in the BRAF gene, and 28% (7/25) presented mutations in both the BRAF gene and the NRAS gene." (PMID 32775409, 2020). "The number of the mutated gene BRAF was found in 12 melanomas from 8 patients." (PMID 32083130, 2020). "Consequently, chemotherapies using small molecule inhibitors of mutated BRAF, such as vemurafenib and dabrafenib, have generated positive clinical responses in approximately half of BRAF-mutated melanoma patients." (PMID 32340351, 2020). "Moreover, the kinase-impaired D594 BRAF mutation is associated with the PIK3CA mutation in the mTOR pathway in melanoma." (PMID 33198372, 2020). "However, the BRAF mutation status of primary malignant melanoma of the lung has only been analyzed in 9 previous cases, and other types of mutations have only been analyzed in 3 previous cases." (PMID 32028967, 2020). "Overview of techniques used for the detection of BRAF mutation in cfDNA from melanoma patients." (PMID 32695793, 2020). "The patients all had confirmed BRAF V600E/K mutation in their melanoma on molecular analysis." (PMID 33139839, 2020). "Eighteen patients (30%) had BRAF WT melanoma, among whom 13 were NRAS-mutated." (PMID 32585901, 2020). "NRAS and BRAF mutations are usually mutually exclusive in melanoma." (PMID 32054078, 2020). "Similarly, the most recurrent tandem mutation in a melanoma driver gene is an AC>TT substitution that causes the BRAF V600K mutation." (PMID 33207206, 2020). "BRAF p.V600E was the most frequent alteration (49.0% of mutated melanoma samples)." (PMID 32340363, 2020). "In the BRIM-3 randomized, phase III clinical trial, the effect of vemurafenib on PFS and OS rates was compared with standard chemotherapy treatment (dacarbazine) in advanced-stage previously untreated melanoma patients harboring a BRAF exon 15 p.V600E point mutation." (PMID 33260892, 2020). "According to the literature, melanoma frequently harbors the BRAF (V600E) mutation." (PMID 32430073, 2020). "Indeed, in a cohort of 138 patients with BRAF V600E-mutated melanoma, 40 cases (29.0%) showed EZH2 gain." (PMID 32850962, 2020). "BRAF mutations are considered to be one of the earliest events in melanoma development." (PMID 32168325, 2020). "While prior in vitro and clinical studies have correlated MAP2K1 missense mutations with resistance to targeted inhibitors in the context of BRAF-mutated melanomas, targeted therapy for melanoma with MAP2K1 in-frame deletion has not been reported to our knowledge." (PMID 32483240, 2020). "Recent data support the hypothesis that these therapies also provide clinical benefit in melanoma patients with activating BRAF mutations." (PMID 32784823, 2020). "BRAF mutations occur in approximately 50% of melanoma patients." (PMID 32382617, 2020). "Finally, we evaluated the presence of BRAF splicing variants in EV RNA isolated from plasma of two melanoma patients failing BRAF inhibition." (PMID 33216826, 2020). "The BRAF V600 mutation has been associated with different histomorphological characteristics of nevi and with the association between the total number of nevi and superficial spreading melanoma." (PMID 32775409, 2020).
melanoma (continued). "From 70, up to 88% of BRAF mutations are represented by V600E (valine to glutamic acid), but V600K (valine to lysine substitution) or V600D (valine to aspartic acid) and V600R (valine to arginine) are found in 5–12% and ≤ 5% of melanomas, respectively." (PMID 32695793, 2020). "The current state of molecular-target drugs and the current therapeutic scenario for patients with BRAF mutated melanoma, from the introduction of BRAF inhibitors as single agents to modern clinical practice, has been extensively described in a related minireview." (PMID 32850962, 2020). "In a study aiming to define whether BRAF V600E could represent a suitable marker for melanoma detection, this mutation was identified only in ctDNA from stage III–IV melanoma patients, whereas, in early stages, it was undetectable in the majority of the cases." (PMID 33050536, 2020). "Dabrafenib is approved for melanoma tumors with BRAF V600E/K mutations." (PMID 33256089, 2020). "Similarly, combining BET with BRAF inhibitors synergized to increase cell death and reduce tumor cell proliferation in BRAF V600E mutated melanoma." (PMID 32046099, 2020). "Mutations in the serine/threonine kinase BRAF are found in 40% of melanomas." (PMID 33216826, 2020). "In the last 10 years, the discovery of high mutation rate of B-Raf Proto-Oncogene (BRAF) in melanoma provides the patients with the choice of drugs targeting BRAF that is involved in mitogen-activated protein kinase (MAPK) pathway, which has significantly improved the patients’ survival." (PMID 32532957, 2020). "This compound and related ROS activated pro-drugs could be useful therapeutic agents where a BRAF inhibition has failed as the first line of treatment in melanoma patients harboring BRAFV600E mutation." (PMID 32092958, 2020). "Up to 70% of melanomas exhibit activating mutations within the kinases BRAF gene and approximately 15% of melanomas within NRAS gene, resulting in constitutive and sustained activation of downstream targets, RAS–MEK–ERK1/2 axis, in addition to unresponsive negative feedback mechanisms." (PMID 33212834, 2020). "Moreover, epidemiological data indicate that the BRAF V600K mutations are associated with melanomas occurring in chronic sun-exposed areas of the head and neck, and are more prevalent in geographical regions with higher ambient UV light." (PMID 33207206, 2020). "Dabrafenib is a potent selective small-molecule inhibitor of BRAF kinase that is orally bioavailable and FDA-approved for treating multiple cancers with activated BRAF (BRAF V600E or V600K mutations) such as melanoma, small cell lung carcinoma, thyroid, and biliary tract cancers." (PMID 33268358, 2020). "Additionally, mutations were common in melanoma, including BRAF (50%), NRAS (30%), MAP2K1 (6%), and KIT (2.6%)." (PMID 33133157, 2020). "A number of studies have reported that melanoma patients with the BRAF V600E mutation treated with BRAF inhibitors could achieve complete or partial response according to the Response Evaluation Criteria in Solid Tumors (RECIST)." (PMID 32476297, 2020). "Finally, the anti-PD-L1 atezolizumab was recently approved by FDA for BRAF V600 mutated, advanced melanoma in combination with the BRAF and the mitogen-activated protein kinase (MEK) inhibitors vemurafenib and cobimetinib, respectively." (PMID 33212945, 2020). "A better knowledge of the genetic and epigenetic changes of BRAF mutations through gene sequencing, as well as a fuller understanding of the underlying pathogenicity of melanoma, should help direct future targeted treatments and the development of a personalised approach to patient management." (PMID 32645969, 2020). "Consistent with this hypothesis, a significant fraction of the UV-induced TRP+ revertants in our yeast assay were CA>TT tandem substitutions, a mutation class that causes the complex BRAF V600E variant in melanoma." (PMID 33207206, 2020). "Mutations that activate BRAF functions are present in over 60% of all melanomas." (PMID 33240890, 2020).
melanoma (continued). "The mutation profile of melanoma of unknown primary is similar to cutaneous melanoma, with frequent BRAF (~50%) and NRAS (~20%) mutations." (PMID 32718045, 2020). "In addition, ropivacaine and lidocaine but not bupivacaine significantly augmented the in vitro efficacy of vemurafenib (a B-Raf inhibitor for melanoma with BRAF V600E mutation) and dacarbazine (a chemotherapeutic drug)." (PMID 32085741, 2020). "The high prevalence of mutations suggest that many Indonesian melanoma cases may benefit from molecular testing and targeted therapy, but more sensitive detection methods are needed for BRAF V600 mutation status testing." (PMID 32188503, 2020). "We have confirmed the regulation of four exemplary genes, namely RAD51, BRCA1, BRCA2, and XRCC2 by vemurafenib treatment in further BRAF-mutated melanoma cell lines using RT-qPCR analysis at the mRNA level and the regulation of Rad51 at protein level using immunoblot analysis." (PMID 32719412, 2020). "The dramatic improvements in the outcomes in BRAF-mutated melanoma patients receiving BRAF and MEK inhibitors highlights the need for molecular assessment, which has become a necessary step to identify patients who are best suitable for targeted therapies or immunotherapies." (PMID 32695793, 2020). "BRAF inhibitors are well-established compounds to target BRAF mutations in melanoma patients." (PMID 32213878, 2020). "In addition, patients with rare melanoma subtypes, such as acral and mucosal, are genetically distinct from cutaneous melanomas and typically lack BRAF-V600E/K mutations, making them ineligible for BRAF/MEK inhibition." (PMID 32764384, 2020). "Even though solar ultraviolet exposure is the main environmental risk factor for cutaneous melanoma development, there are still genetic susceptibility factors, such as germline mutations in p16 or CDK4, and genesis of melanoma, such as the main genetic drivers BRAF, NF1 and NRAS mutations." (PMID 32333246, 2020). "In melanoma, an activating point mutation at V600 in BRAF is the main oncogenic driver." (PMID 32260561, 2020). "Also, based on other studies, V600E mutation is the most common BRAF mutation in melanoma, occurring in 70–90% of BRAF mutant melanomas." (PMID 33282420, 2020). "This is the case for the sensitivity to HER2-inhibitors for tumors with ERBB2 amplification in breast cancer, the vemurafenib sensitivity of BRAF-mutant cells in melanoma, or the relevance of EGFR mutation for EGFR-inhibitor treatments in non-small cell lung cancer (NSCLC)." (PMID 32645997, 2020). "The constitutive activation of the BRAF/MEK/ERK pathway is a hallmark of melanoma." (PMID 33396645, 2020). "The V600E BRAF mutation constitutes over 90% of all BRAF mutations in melanoma." (PMID 32556513, 2020). "In about 60% of melanomas, the protein kinase BRAF is mutated (BRAFV600E)." (PMID 33202765, 2020). "In particular, about 50% of melanoma is characterized by the presence of BRAF activating mutations." (PMID 32392801, 2020). "2-PCPA-1a, an inhibitor of LSD1, promotes oncogenic BRAF mutation-induced OIS in melanoma cells." (PMID 32081882, 2020). "In advanced/metastatic disease, systemic first-line therapeutic options are specific BRAF-inhibitors for BRAFV600E-mutated melanomas as well as immune checkpoint inhibitors but the understanding of emergence of acquired resistance to these therapies is still an unmet clinical need." (PMID 31906510, 2020). "In addition, ERK-induced TFEB phosphorylation impaired expression of autophagy-lysosome target genes in BRAF-mutated melanoma, which elicited the formation of TGF-β-dependent metastases." (PMID 32858889, 2020).
melanoma (continued). "The application of targeted therapy, including BRAF inhibitors (e.g., vemurafenib (VEM) and debrafenib) and mitogen-activated protein kinase kinase (MEK) inhibitors (e.g., trametinib (TRA) and cobimetinib), was regarded as a therapeutic breakthrough when used in patients with BRAF-mutated melanoma." (PMID 33396632, 2020). "The melanoma patients were first classified according to the status of BRAF and NRAS mutation." (PMID 32411243, 2020). "IL-1α is another interleukin produced by BRAF mutated melanoma cells." (PMID 32517213, 2020). "Ribociclib also showed some activity in melanomas with activating mutations of BRAF or NRAS." (PMID 32850962, 2020). "The discovery of BRAF V600 mutation and the development of targeted therapies directed against this mutation as well as effective immunotherapies with durable benefits have revolutionized the treatment of patients with melanoma." (PMID 33282420, 2020). "In melanoma, RhoB deficiency causes hypersensitivity to BRAF and MEK inhibitors-induced apoptosis." (PMID 32244473, 2020). "Indeed, it has been demonstrated that mutated BRAF negatively regulated oxidative metabolism in melanoma cells, while BRAF inhibitors enhanced dependence of melanoma cells on the oxidative phosphorylation (OXPHOS)." (PMID 32340261, 2020). "Oncogenic mutations in BRAF have been identified in ~50% of melanoma cases." (PMID 32371878, 2020). "The presence of this mutation in melanoma cell lines causes resistance to BRAF inhibitors." (PMID 32605090, 2020). "Another study reported the association of BRAF mutation with poorer MSS in melanoma patients." (PMID 32143442, 2020). "BRAF mutations are observed in most melanocytic nevi (70–80%), metastatic melanomas (40–50%), and vertical growth phase melanomas (40–50%), and might be an acquired event in early invasive melanoma that induces clonal expansion and tumor progression." (PMID 32556513, 2020). "The chosen melanoma cell lines have both wildtype (WT) and mutated BRAF." (PMID 32085796, 2020). "Further, we performed in vitro studies of the effects of flavonolignans on mechanisms including the targets of the corresponding drugs—BRAF V600E kinase activity, the viability of A-375 human melanoma cells (with BRAF V600E mutation), and Hedgehog (HH) signaling pathway, including SMO." (PMID 32380762, 2020). "RASA2 mutations co-occurred in NF1 mutant melanomas that were BRAF-RAS wild type, in a WES study of 213 melanoma samples (62 cell lines and 151 melanomas); 12.2% (26/212) of melanomas were NF1-mutant/BRAF-RAS-wild-type and nine of them harbored co-mutations in RASA2 (2 nonsense and 3 R551C)." (PMID 32850962, 2020). "Therapies targeting the BRAF V600E mutation help advanced melanoma patients live longer." (PMID 32858889, 2020). "Therefore, several generations of mutation-specific small molecule BRAF inhibitors were developed, initially mainly for the use in the treatment of malignant melanoma, where BRAF mutations are most common." (PMID 33256240, 2020). "The inhibition of this enzyme using selective COX-2 inhibitors in BRAF- or NRAS-mutated melanoma may represent a reasonable and clinically feasible option to help inhibit tumor progression and induce tumor cell death." (PMID 32296574, 2020). "Consequently, BRAF mutation is associated with poor prognosis in not only melanoma but also papillary thyroid cancer and metastatic colon cancer." (PMID 32556513, 2020). "BRAF mutations are more frequent in melanomas that develop in sun-exposed skin." (PMID 32054078, 2020). "It is possible that in the reactivated, BRAF-mutated melanoma cells, there exists a signaling network including the ER stress, MAPK/ERK, and cAMP/PKA signaling pathways, which interact with each other and play an integral role in the self-survival of tumor cells." (PMID 33396632, 2020). "Therefore, the BRAFV600E mutation acts as a pivotal oncogenic driver gene in melanoma, leading to the development of targeted BRAF kinase inhibitors." (PMID 32021565, 2020).
melanoma (continued). "Even in this case, the combination of the two drugs significantly improved OS and PFS rates in previously untreated advanced-stage BRAF exon 15 p.V600-mutated melanoma patients treated with the combination therapy compared with vemurafenib plus placebo (control group)." (PMID 33260892, 2020). "This hypothesis is supported by the finding that alterations of the expression of genes belonging to “MSCsign” is associated with the worst OS for BRAF mutated melanoma patients based on TCGA data." (PMID 33202944, 2020). "PD1/PDL1 therapy currently is also in phase III clinical trials for the indications of BRAF V600-mutated melanoma, RCC, head and neck squamous cell carcinoma (HNSCC), nasopharyngeal cancer, esophageal carcinoma, mesothelioma, hepatocellular carcinoma, breast cancer, and multiple myeloma." (PMID 32517713, 2020). "Regardless of whether BRAF and/or MAPK inhibitors are administered sequentially or in combination with an immune checkpoint inhibitor, treatment with both agents leads to more durable responses in patients with BRAF-mutated melanoma." (PMID 32260561, 2020). "The Cancer Genome Atlas Network has recently provided a potential step ahead in the comprehension of melanoma genesis, proposing a classification of melanoma based on protein, RNA and DNA analysis from over 300 melanoma patients, in addition to BRAF, NRAS, and NF1 mutational profile." (PMID 33233603, 2020). "However, the mutation rate of the BRAF V600 gene of melanoma patients in China is only 25%, which is lower than the rate of 50–60% found in western countries." (PMID 32903487, 2020). "Together with targeted therapy for BRAF mutated patients, the backbone of treatment in advanced melanoma is represented by the immune therapy with either anti-CTLA4 or anti-PD1 agents, that remove immune checkpoint inhibition to potentiate the immune response to melanoma." (PMID 33193402, 2020). "Furthermore, in mouse models of BRAF-mutated melanoma, inhibition of PI3K cooperated with ERK pathway inhibition to forestall the onset of MAPK pathway inhibitor resistance." (PMID 32531927, 2020). "The first gene examined is BRAF, given its high frequency of mutations in melanoma (36–52%)." (PMID 32054005, 2020). "In the COLUMBUS phase III clinical trial, previously treated or untreated advanced-stage melanoma patients harboring BRAF exon 15 p.V600E or p.V600K point mutations were randomly assigned to receive the combination regimen or single BRAF inhibitor therapies (vemurafenib or encorafenib)." (PMID 33260892, 2020). "In addition to immunotherapy, patients with melanoma can also benefit from anti-BRAF therapy when a mutation is detected." (PMID 33266349, 2020). "However, ~80% of benign melanocytic nevi contain BRAF-activating mutation, although only a small percentage of them will develop into malignant melanoma." (PMID 32373541, 2020). "This is a retrospective analysis that included 161 patients with BRAF V600E or neuroblastoma RAS viral oncogene homolog (NRAS) pQ61L/K mutated melanoma in primary tumor and in which the presence of the same mutations in ctDNA was analyzed within 12 weeks after surgery using dPCR." (PMID 32629823, 2020). "Mouse melanoma model carrying the frequent mutation of the BRAF oncogene (V600E) and PTEN deletion shows the repression of a protective immune response in the TME which was counteracted by an autophagy inducer, metformin, which determines tumor growth inhibition." (PMID 32708484, 2020).